RNU6-709P (RNA, U6 small nuclear 709, pseudogene)
Gene: Small nuclear RNA gene on chromosome 10 (114,111,414 to 114,111,517, forward strand). Ensembl gene ENSG00000253066.
Homologues: Orthologues: chimpanzee U6 (99% identical). Paralogues in human: RNU6-1189P (77% identical), RNU6-1103P (75% identical), RNU6-128P (75% identical), RNU6-33P (75% identical), RNU6-38P (75% identical), RNU6-698P (75% identical), RNU6-891P (75% identical), RNU6-1 (74% identical), RNU6-1020P (74% identical), RNU6-1026P (74% identical), RNU6-1179P (74% identical), RNU6-140P (74% identical), and 1285 more.